TBR1 (T-box brain transcription factor 1)
Diseases named in the same sentence as TBR1 in open-access papers (continued):
Sharing a sentence is not in itself a finding about the gene and the disease.
psychiatric disorder (2 papers, 2014 to 2021). A disorder characterized by behavioral and/or psychological abnormalities, often accompanied by physical symptoms. "Since Tbr1 has been shown to directly regulate the expression of Grin2b and Tbr1 plays roles in psychiatric disorders, Tbr1 is a likely candidate that senses the neuronal stimulations and regulates glutamatergic pathways." (PMID 25309323, 2014). "TBR1 has also been associated with ASD and TCF4 with BPD, and TOP3B was shown to bind multiple mRNAs derived from ASD-linked genes, raising the possibility that STX1A-mediated neurotransmitter release is dysregulated in multiple psychiatric disorders." (PMID 31142819, 2021).
kidney diseases (1 paper, 2022). "Among the predicted mRNAs, S1PR5, STAT3, TBR1, and BMPR1B were found to be related to some kidney diseases, as well." (PMID 36536378, 2022). "Moreover, among the predicted targeted mRNAs, S1PR5, STAT3, TBR1 and BMPR1B were found to be related to some kidney diseases." (PMID 36536378, 2022).
TBR1 also shares sentences with these, for which no sentence is quoted: Cognitive impairment (2 papers); language delay (2); B-Cell CLL (1); bipolar disorder (1); brain disorder (1); cortical dysplasia (1); depressive disorder (1); glioma (1); Hyperglycemia (1); Lissencephaly (1); lymphoma (1); medulloblastoma (1); metastatic disease (1); MICPCH syndrome (1); oligodendroglioma (1); X-linked intellectual disability (1).